IGFBP2 (insulin like growth factor binding protein 2)
Diseases named in the same sentence as IGFBP2 in open-access papers (continued):
Sharing a sentence is not in itself a finding about the gene and the disease.
glioblastoma (continued). "While high grade glioblastoma, which are frequently observed to have elevated IGFBP2 level, also have regions of reduced IGFBP2 expression, which have been shown to be at the invasive front of the tumor." (PMID 25774149, 2015). "There have not been any published drugs that have specifically blocked feedback between IGFBP2 and HIF1α in glioblastoma." (PMID 25884993, 2015). "Our results from the growth reduction analysis showed that glioblastoma growth was more sensitive to the removal of feedback from IGFBP2 to HIF1α as compared to the IGFI to HIF1α interaction." (PMID 25884993, 2015). "In our previous study, high serum IGFBP-2 level was related to poor prognosis in glioblastoma patients." (PMID 25880463, 2015). "In our previous study, we demonstrated that serum IGFBP-2 levels were inversely correlated with survival in glioblastoma patients." (PMID 25880463, 2015). "Elevated plasma IGFBP-2 levels after combined postoperative radiotherapy and chemotherapy in elderly glioblastoma patients correlate with poor KPS score and predicts poor prognosis." (PMID 24690948, 2014). "Reactivation of IGFBP-2 expression in glioblastoma multiforme was discussed in a context of defect astrocyte differentiation and PI3K/AKT activation." (PMID 24778626, 2014). "The important role of IGFBP-2 in malignant brain tumors, particularly glioblastoma, has already been mentioned." (PMID 24778626, 2014). "Plasma IGFBP-2 levels in 83 glioblastoma patients after postoperative radiotherapy plus chemotherapy were analyzed using an IGFBP-2 ELISA kit." (PMID 24690948, 2014). "Plasma IGFBP-2 levels significantly correlated with overall survival in glioblastoma patients (multivariate HR = 1.035; 95% CI, 1.024–1.047; P<0.001)." (PMID 24690948, 2014). "Elevated expression of IGFBP2 has been observed in multiple malignancies, including Glioblastoma multiforme, ovarian, pancreatic, gastric, prostate, colon, breast, leukemia and thyroid cancer." (PMID 23767917, 2013). "In our microarray experiments, we observed the induction of Igfbp2, a gene that has also been shown to regulate the proliferation, invasion, and angiogenesis of glioblastomas." (PMID 23533150, 2013). "From these genes of particular interest are HEY2 with a role in notch signaling, LEFTY2 involved in TGFβ-signaling and IGFBP2 which is overexpressed in the stem cell compartment of glioblastomas promoting proliferation and survival of brain tumors." (PMID 24236059, 2013). "IGFBP2 is known to be overexpressed in a majority of glioblastoma tumors, and its expression is inversely correlated to glioblastoma patient survival." (PMID 24212792, 2011). "Overexpression of Igfbp2 has also been correlated with glioblastoma and lymph node metastasis in patients with invasive breast carcinomas." (PMID 20808936, 2010). "This, in combination with analysis of glioblastoma formalin-fixed paraffin-embedded tissue samples identified a nine-gene signature including IGFBP-2, chitinase-3-like protein 1 (CHI3L1)/YKL-40, galectin 3 (LGALS3) and OLIG2 that was predictive of worse clinical outcomes." (PMID 40429889, 2025). "Additionally, various diseases like cancer—particularly glioblastoma and prostate cancer—as well as metabolic disorders such as type 2 diabetes (T2DM) and insulin resistance are associated with elevated IGFBP-2 levels." (PMID 39585162, 2024). "Furthermore, TCGA analysis reveals that IGFBP2 is up-regulated in classical glioblastoma, reputed for high Nestin expression." (PMID 36430641, 2022). "In glioblastoma cells, by elevating a group of molecules associated with cell migration signalling pathways, such as connective tissue growth factor (CTGF) mRNA and insulin-like growth factor binding protein 2 (IGFBP2), radiation enhanced the migration of recipient cells." (PMID 33789758, 2021).
glioblastoma (continued). "Some publications have suggested that IGFBP2 plays a tumor promotor role in glioblastoma through activation of β-catenin or EGFR–STAT3 pathways, pancreatic ductal adenocarcinoma via activation of the NF-κB pathway, and prostate cancer cells by the androgen-mediated pathway and MAPK-PI3K pathway." (PMID 33282953, 2020). "Finally, it should be mentioned that IGFBP2 most likely plays an important role in the immunologic processes of glioblastomas including immunosuppressive checkpoints and various signaling pathways." (PMID 31296788, 2019). "In summary, IGFBP2 mRNA served as an independent prognostic biomarker in glioblastomas." (PMID 31296788, 2019). "Well, the answer is that studies of IGFBP2 transcript expression in glioblastoma biopsies detected by an in situ method were very few, but as of today, the techniques have been improved and could either confirm or challenge previous results." (PMID 31296788, 2019). "The identification of a regulatory loop whereby miR-302b inhibits NFIA, leading to a decrease in expression of IGFBP-2, may provide novel directions for developing therapies to target glioblastoma tumorigenesis." (PMID 28323865, 2017). "We found that glioblastoma growth was highly sensitive to this new hypothesized interaction, IGFBP2 to HIF1α signaling." (PMID 25884993, 2015). "In fact, the top four rate constants that glioblastoma growth was most sensitive to when individually perturbed were the production of HIF1α (k8), production of IGFBP2 (k1), growth rate due to HIF1α (k11) and promotion of HIF1α by IGFBP2 (k10)." (PMID 25884993, 2015). "Our model highlights a key driver for the growth of glioblastoma: IGFBP2-HIF1α feedback." (PMID 25884993, 2015). "Removal of the HIF1α to IGFBP2 connection had minimal effect on the glioblastoma growth." (PMID 25884993, 2015). "In addition, high expression of ADAMTS1 correlates with higher levels of cleaved IGFBP2 in glioblastoma multiforme cases." (PMID 24962328, 2014). "In addition, increased expression of IGFBP2 has been correlated with poor prognosis in prostate, glioblastoma and colon cancers." (PMID 23767917, 2013). "Interestingly, IGFBP2, one of the most significant gene changes between the two subgroups of glioblastomas showing different TGFβ responses (fold change 7.37, p < 1.27 × 10-9), has been shown to enhance glioblastoma invasion." (PMID 19192267, 2009). "Since IGFBP2 and VEGFA mRNA were significantly associated with elevated macrophages in the dormant state (M0) and decreased anti-inflammatory state (M2), the authors suggest that elevated IGFBP-2 secretion from GSCs could be an important factor for shaping the glioblastoma immune microenvironment." (PMID 40429889, 2025). "This study developed a prognostic signature using hypoxia-related differentially expressed genes (DEGs) in Glioblastoma Multiforme (GBM) and identified three optimal gene signatures (CP, IGFBP2, and LOX) using multi-omics analysis." (PMID 38339384, 2024). "Thus, targeting the insulin signaling pathway through the IGFBP2-HIF1α interaction could be effective for those glioblastoma cells dependent on insulin signaling." (PMID 25884993, 2015). "Therefore, during glioblastoma-induced inflammatory responses, the interaction among albumin, IGFBP-2 and IL-6 may greatly affect clinical outcomes." (PMID 25880463, 2015). "Due to the overexpression of IGFBP2 within tumour tissue, many studies focus on the functions of IGFBP-2 in glioblastoma." (PMID 40429889, 2025). "Previous studies have demonstrated that IGFBP2 binds to integrin α5β1 and αvβ3 to trigger PI3K and MAPK signalings in glioblastoma cells." (PMID 38918360, 2024). "In glioblastoma, nuclear IGFBP2 leads to aberrant EGFR and STAT3 signaling in vitro, and RCAS-mediated IGFBP2 expression increased glioblastoma formation and progression in vivo in a mouse model, which was reversed when IGFBP2 expression was inactivated." (PMID 37029430, 2023).
glioblastoma (continued). "For example, IGFBP2 can serve as a potential marker for PI3K/Akt pathway activation and PTEN status in prostate cancer as well as glioblastoma." (PMID 37088808, 2023). "Immunohistochemistry was used to quantify IGFBP‐2 and GRP78 expression in IDH‐wildtype glioblastoma tissue sections (n = 92) and clinical implications assessed using survival analysis." (PMID 37212470, 2023). "Critically, the negative regulation between IGFBP‐2 and PTEN has been shown to be of clinical importance in triple negative breast cancer, glioblastoma and prostate cancer." (PMID 37212470, 2023). "In the case of glioblastoma cell lines, an elevated level of connective tissue growth factor (CTGF) and insulin-like growth factor-binding protein 2 (IGFBP2) have been reported." (PMID 35735486, 2022). "Our study shows the cells grown in 3D-GMH with serum overexpress and secrete CXCL1, CXCL5, IGFBP2, PTX3, THBS1, VEGFA, and VCAM1—all genes expressed in perivascular or perinecrotic zone of glioblastoma tissues that are hotspots for immune cells." (PMID 34489494, 2021). "IGFBP2 was previously reported to augment the nuclear accumulation of EGFR and to potentiate STAT3 transactivation via nuclear EGFR signaling pathway in glioblastoma." (PMID 31801484, 2019). "Fn14 was found to be co-expressed with IGFBP2 and 3 and VEGFA, IFNγR2, TNFR1A and IGFBP2 and lamin A, suggesting a possible role of this receptor in glioblastoma angiogenesis." (PMID 24376672, 2013). "This cluster contained several genes well-known to be overexpressed in glioblastomas (IGFBP2, CHI3L1) and markers of glioblastoma cancer stem cells as well (CD133, IQGAP1)." (PMID 18492260, 2008). "Similarly, the interaction between IGFBP-2 and integrin α5β1 in SNB19 glioblastoma cells overexpressing IGFBP-2 was shown to activate JNK with downstream cell migration enhancement." (PMID 40429889, 2025). "Inverse levels of IGFBP‐2 and GRP78 may be adverse clinical prognostic markers in IDH‐wildtype glioblastoma." (PMID 37212470, 2023). "Taken together, our experimental and clinical findings suggest that inverse levels of IGFBP‐2 and GRP78 may be adverse clinical prognostic markers in IDH‐wildtype glioblastoma." (PMID 37212470, 2023). "Likewise, IGF-1, IGFBP2, SPARCL1, kininogen-1, osteopontin, and GRP78 are known to be secreted by glioblastoma cells." (PMID 35659255, 2022). "IGFBP2 induced immunosuppression by decreasing CD8+ T and CD19+ B cells and increasing CD163+ M2 TAMs; blocking this gene suppressed tumor growth and improved survival in a glioblastoma mouse model." (PMID 33790966, 2021). "Meanwhile, K-M curves confirmed that these three genes (CCL2, IGFBP2, and PDPN) could be used as independent predictors of survival in patients with glioblastoma." (PMID 32296458, 2020). "When a similar simulation was conducted for the U87 cell line, there was not a significant change in the glioblastoma volume when either the IGFBP2 to HIF1α or the IGFI to HIF1α connection was removed, see S5 Fig." (PMID 25884993, 2015). "However, this does not explain the overexpression and prognostic effect of IGFBP-2 in glioblastoma studies." (PMID 40429889, 2025). "We speculate that this study, which utilized adult glioblastoma as a positive control, may not have detected the expression of alternate IGFBP2 isoforms in pediatric MB." (PMID 37029430, 2023). "In addition, cadherin-5, VEGF, IGFBP2, and MMP2 (MMP2 was detected in two glioblastoma cyst fluid samples are involved in the generation of vasculogenic mimicry in glioblastomas." (PMID 35659255, 2022). "Interestingly, our analysis of 135 cases of TCGA glioblastoma data also showed a 2-month statistical advantage in the median overall survival with low IGFBP2 mRNA levels (data not shown)." (PMID 27852048, 2017). "This work demonstrated a correlation between a cleaved N-terminal fragment of IGFBP2 and the protease ADAMTS1 in glioblastoma suggesting IGFBP2 is not in a full-length form and therefore may be unable to bind IGFs." (PMID 25774149, 2015).
glioblastoma (continued). "The underlying mechanism may be that a high concentration of exogenous IGFBP-2, possibly resulting from blood–brain barrier (BBB) leakage, stimulates proliferation, invasion, and chemoresistance to temozolomide in glioblastoma cells via the integrin β1-ERK pathway." (PMID 25880463, 2015). "Similarly, given their preserved receptor activation capacity, but potentially altered affinity for IGF-binding proteins, including IGFBP-2, it is plausible that high-molecular-weight IGF-II may differentially modulate IGF bioavailability and receptor activation in the glioblastoma microenvironment." (PMID 40429889, 2025). "IGFBP2 was correlated with M2 Macrophages, CD8+ T cells, which enhanced the immunosuppression of glioblastoma and it might be an effective immunotherapeutic strategy for glioblastoma therapy; However, there are no similar reports relating to IGFBP2 and DCs." (PMID 37006311, 2023).
prostate carcinoma (55 papers, 2005 to 2025). A carcinoma that arises from epithelial cells of the prostate gland. "IGFBP2 has shown diagnostic and prognostic potential in glioma, prostate cancer, and ovarian cancer." (PMID 39221034, 2024). "There was some evidence of heterogeneity by study in the associations of IGF-I with aggressive disease (Phet = 0.02), and IGF-II and IGFBP-2 with overall prostate cancer risk (Phet = 0.0001 and 0.02, respectively)." (PMID 35726641, 2023). "Only men with lower total testosterone concentrations had a positive association between IGFBP-2 and overall prostate cancer (Phet = 0.01)." (PMID 35726641, 2023). "Previously, when we examined concentrations of IGF axis analytes in serum of subjects in relation to prostate cancer risk in the PCPT, IGFBP-2 was found associated with increased risk for prostate cancer in the placebo arm." (PMID 28417914, 2017). "Earlier reports have shown that high expression of annexin-1, caveolin-1, caveolin-2, moesin, and uPA, as well as low expression of IGFBP2, was associated with the in vitro response to dasatinib in breast, lung, and prostate cancer cells." (PMID 19861960, 2009). "There was evidence of heterogeneity in the association of IGFBP-2 with overall prostate cancer by BMI (Phet = 0.0007); for men whose BMI was <25 kg/m2 at baseline, IGFBP-2 was inversely associated with prostate cancer (0.89: 0.83, 0.96), and the OR for men with BMI 30+ was 1.19 (0.99, 1.42)." (PMID 35726641, 2023). "In TCCSUP cells, as the increase in demethylation in response to AZA was small, we suggest that other epigenetic changes such as histone modification, which has been reported in prostate cancer, might also contribute to the loss of IGFBP-2." (PMID 31903164, 2019). "We did not observe an increased risk of prostate cancer with higher serum IGF-2 in the PCPT when analyzed previously, in either finasteride or placebo treatment arms, although men in the highest quartile of serum IGFBP-2 had increased risk of total and low-grade prostate cancers." (PMID 28417914, 2017). "The association of increased blood IGFBP2 with shorter overall survival reported here in lung cancer patients and by others in ovarian cancer, colorectal cancer, and prostate cancer suggests that IGFBP2 may contribute to malignant evolution and progression." (PMID 24069370, 2013). "Fifteen studies investigated whether genetic or epigenetic variations in the IGF-I (n = 5), IGF-II (n = 7), IGFBP-2 (n = 2) or IGFBP-3 (n = 3) gene were associated with prostate cancer risk or outcomes such as Gleason score, TNM stage, PSA recurrence or survival." (PMID 28361446, 2017). "Elevated plasma IGFBP2 levels correlate with malignancy risk in prostate cancer NSCLC studies link IGFBP2 overexpression to gefitinib resistance, reduced survival, and increased metastasis." (PMID 40821817, 2025). "We aimed to investigate the associations of IGF-I, IGF-II, IGFBP-1, IGFBP-2 and IGFBP-3 concentrations with overall, aggressive and early-onset prostate cancer." (PMID 35726641, 2023). "IGFBP2 also promotes STAT3 activity in prostate cancer invasion and promotes NF-κB-driven invasion in pancreatic cancer." (PMID 37029430, 2023). "For instance, IGFBP-2 enhanced proliferation of androgen-independent prostate cancer cells and IGF-I levels were found raised in serum and prostate tissue from PCa patients, being a predictor of risk for this type of cancer." (PMID 35454907, 2022). "In particular, ABI treatment reduced the OB release of IGFBP2, 4 and 6 proteins, known to be directly involved in prostate cancer progression via IGF-dependent and independent mechanisms." (PMID 36140255, 2022). "miR-34a-5p downregulation in prostate cancer is responsible for the overexpression of HIF1A, IGFBP2 and PIK3CB, associated with tumor development and progression." (PMID 35741059, 2022). "We analysed the levels of FOXA1 and IGFBP-2 in a panel of prostate cancer and normal prostate epithelial cells." (PMID 32655839, 2020).